MYC (MYC proto-oncogene, bHLH transcription factor)
Diseases named in the same sentence as MYC in open-access papers (continued):
Sharing a sentence is not in itself a finding about the gene and the disease.
tumor (continued). "These correlations showed that when c-MYC gene expression was diminished by treatment with CisPt and/or RSV, the apoptotic process was hampered, and we can consider this a weaker response of PE/CA-PJ49 tumor cells to CisPt." (PMID 34204834, 2021). "The low level of HOXB8 reduced the OS of ccRCC; however, we found that HOXB8 may also control tumor invasion by inhibiting CCND1 and MYC in the Wnt signaling pathway." (PMID 34306077, 2021). "Despite JQ1’s effective inhibition of tumor growth via suppression of MYC transcription, it showed no apparent inhibitory effects on tumor invasion and metastasis." (PMID 34761120, 2021). "In addition, we examined protein levels of several LPS141 tumor-promoting genes (i.e., RUNX1, c-MYC, FOSL2, RUNX2, and SNAI2) after ETC-168 treatment." (PMID 33564073, 2021). "The overexpression of the MYC gene has a negative impact on the tumor stage, tumor metastasis, lymph node metastasis, tumor diameter enlargement, and other poor prognosis factors of patients." (PMID 33540574, 2021). "The administration of synthetic miR-28a-5p mimicked using a liposome delivery approach, impaired proliferation and survival of lymphoma cells, and abrogated tumor growth in MD901 DLBCL and Ramos human BL xenograft mouse models and in a λ-MYC transgenic mouse BL model." (PMID 34944942, 2021). "Undoubtedly, the well-described effects of MYC on global transcription and protein production, CCND1 on cell cycle transition, and KIF18A on chromatin segregation contribute greatly to YAP-mediated in vivo tumor expansion." (PMID 33514403, 2021). "In lung cancer, combining HDACi with DNA demethylating agents reduced macrophage infiltration, increased T cell infiltration of the TME with non-exhausted T cells and reduced MYC expression in tumor cells." (PMID 33859645, 2021). "The correlation between oncogene amplification and increased tumor aggressiveness has been extensively studied; nevertheless, since MYC is involved in several cellular pathways, the role of this oncogene in tumor progression has not yet been fully elucidated." (PMID 33430027, 2021). "USP28 inhibitor treatment resulted in a dramatic decrease in c-MYC, c-JUN, and Δp63 proteins levels and consequently induced substantial regression of autochthonous murine LSCC tumours and human LSCC xenografts, thereby phenocopying the effect observed by genetic deletion." (PMID 34636321, 2021). "In agreement with the mixed normal and tumor datasets, PBMC displayed positive correlations between ACE2/TMPRSS2, TMPRSS2/FURIN, ACE2/TFRC, FURIN/TFRC, TMPRSS2/CTSL, FURIN/CTSL, TMPRSS2/MYC, and FURIN/AKT1 and a negative association between ACE2/ADAM17." (PMID 33796097, 2021). "Copy number aberration (CNA) profiling and variant analysis using next-generation sequencing (NGS) showed that these cells did not harbor the alterations exhibited by the primary tumor (PIK3CA G1049A mutation, MYC copy number gain)." (PMID 34249978, 2021). "Protein–protein interaction of the gene in the ceRNA networks shown that the high-scoring proteins were obtained including CD44, MYC, CCND1, ESR1, IL6, and VEGFA, which suggesting that they might jointly regulate the occurrence and development of tumor." (PMID 34655361, 2021). "In a pancreatic β-cell cancer mouse model with inducible expression of a dominant-negative MYC mutant, the study found that inhibition of MYC effectively reduced the degree of infiltrating macrophages and neutrophils, directly impacting tumor regression." (PMID 33917037, 2021). "In addition, METTL3 strengthened the stability of MYC in a METTL3-m6A-YTHDF1-mediated manner, thereby stimulating tumor progression." (PMID 33879256, 2021).
tumor (continued). "The demonstration of cell subpopulations, expressing either multiple markers by the tumor cells or exclusively OCT4 and c-MYC by the stromal cells, suggests these subpopulations may be related to one another." (PMID 34685477, 2021). "Interestingly, those analyses identified c-MYC as a significant upstream regulator and several genes connected to the cellular c-MYC network were hypomethylated in ALK tumor samples." (PMID 33310759, 2021). "c-MYC has been reported to be overexpressed in 20% of NSCLC and contributes to tumor progression." (PMID 34685477, 2021). "A combination of invasion of E-boxes by MYC-MAX and/or binding of E2Fs at target loci may account for the net transcriptional activation of these genes and tumor initiation or progression." (PMID 34236315, 2021). "For instance, a subset of luminal B tumours that also presents ERBB2 amplification was shown to display enhanced glutamine catabolism due to higher MYC activity compared to luminal B tumours without ERBB2 amplification." (PMID 34572926, 2021). "In addition, the SPOP protein plays a role as a tumor suppressor that negatively regulates the stability of multiple other oncogenic substrates in PrCa, including AR, SRC-3, c-MYC, ERG, DEK, BRD4 and Trim24." (PMID 34857003, 2021). "According to studies, the first miRNA could act a tumour suppressor in RCC cell lines via the targeting c-MYC, while the second one is a VHL-regulated tumour suppressor acting through hindering macroautophagy." (PMID 35008576, 2021). "i.e., miR-155, miR-17-92 and miR-21 act as oncogenes by altering the expression levels of MYC, SHIP and FOXO1, respectively, conversely; miR-34a, mir-144 and miR-181a act as tumor suppressors by altering the expression levels of SIRT1, BCL6 and CARD11, respectively." (PMID 34679437, 2021). "However, it can also interact with TFs such as c-MYC, which can transactivate ANRIL and promote tumor progression." (PMID 34072826, 2021). "The c-MYC gene could cooperate with other oncogenes such as BCL-2, and thus it might influence the mechanisms involved in tumor surveillance." (PMID 34204834, 2021). "Also, simultaneous inhibition of BET proteins and blockade of the chemokine receptor CXCR4 potentiated MYC reduction in DLBCL cells and reduced tumor volume of transplanted xenografts." (PMID 35008680, 2021). "IL-6 is shown to inhibit the expression of tumor suppressors, notably BIM and PTEN, and this may contribute to advancing MYC-driven B cell tumorigenesis." (PMID 33651821, 2021). "In detail, c-Myc and Notch1 have been identified among the target genes through which FBXW7 influences skin carcinogenesis by counteracting the proliferation-promoting effect of c-MYC and the tumor-suppressive effect of NOTCH1, respectively." (PMID 32560247, 2020). "We used a panel of SCLC cell lines with exclusive MYC paralog amplification and two SCLC cell lines without MYC paralog amplification or overexpression to assess the anti-tumor effects of JQ1 and BMN673." (PMID 33134168, 2020). "Proteins from transplanted tumor tissues were extracted for Western blot analysis, and the results displayed that levels of FTO, MYC, CDK2, CDK4, Ki-67, PCNA and Bcl-2 proteins in miR-96 antagomir group were downregulated, while AMPKα2 and Bax proteins were raised." (PMID 33183350, 2020). "Using cutoff values of MYC (40%) and BCL2 (50%) positive tumor cells, twenty-eight (32.2%) were diagnosed as double-expressor lymphoma (DEL), thirty-two (36.8%) as non-DEL and twenty-seven (31%) as unknown." (PMID 33123290, 2020). "Glucose metabolism inhibitors targeting MYC have recently shown the ability to inhibit GLUT-1, LDH-A, and MCT1 expression in cancer cell lines, along with decreased MYC activity, resulting in reduced cell proliferation and tumor growth." (PMID 32493394, 2020). "Orthotopic implantation of MYC/Twist1- but not MYC-HCC tumor cells in NSG mice led to pulmonary and intrahepatic metastases with extensive macrophage infiltration." (PMID 31933479, 2020).
tumor (continued). "MYC may suppress the expression of the pro-apoptotic BIM gene, a target of miR-17-92 thus explaining its tumor-promoting function, so contributing to maintaining survival and self-renewal." (PMID 32549409, 2020). "Additionally, numerous targets of expressions which were observed in carcinogenesis and tumor progression were reported to be regulated by miR-34a, such as CD44, BCL2, NOTCH1, CDK4/6, MET, MYC, and many other molecules." (PMID 32391256, 2020). "The MYC copy number revealed by dPCR showed statistically significant differences between tumor and adjacent nontumor tissues." (PMID 33014186, 2020). "Immunohistochemistry revealed that the incidence of positive expression for PD-L1 in tumor tissues were highest in the TSIM subtype, MYC in the MB subtype, and DAXX in the HEA subtype, indicating that molecular subtypes are sensitive to different targeted therapeutic strategies." (PMID 33292562, 2020). "The median MYC copy number in tumor samples was 2.09 (IQR: 1.96–2.34) and in nontumor samples 1.99 (IQR: 1.94–2.06)." (PMID 33014186, 2020). "In addition, HME primary tumor maintained the same pattern after TT, whereas 14 LME patients changed in high c-MYC expression after anti-EGFR therapy (decremental percentage of almost 60%)." (PMID 32164324, 2020). "Furthermore, safranal-treated tumor tissues exhibited a reduction in Skp2, E2F1, NF-κB p65, p-IκBα (Ser32), c-MYC, p-Rb (Ser807), CDK4, CDK6, and CDK2 and an elevation of p27 and p21 protein levels." (PMID 33392189, 2020). "Together, these findings indicate that the cellular behavior of MYC in PCa contrasts with other tumor types, and that MYC does not act solely in a proliferative capacity." (PMID 32681068, 2020). "In primary malignant neoplasm of brain which including three DEGs (CDK4, EZH2, MYC)." (PMID 32696617, 2020). "In contrast, CNV in all 3 exons of MYC were exclusively detected in the serum of one patient, but not in the primary tumor." (PMID 33298978, 2020). "Boosting tumour cell glycolysis by overexpressing MYC, glycolytic enzymes or GLUT-1 increased tumour progression, while suppression of glycolysis by checkpoint blockade therapy restored T cell responses and resulted in tumour regression." (PMID 31102668, 2020). "The researchers speculated that the effects of the ESCM on tumour reversion may result from the exchange of materials between cells, thereby rebalancing the expression of the stemness factors OCT4, SOX2, KLF and c‐MYC in tumour cells." (PMID 32588948, 2020). "MYC can induce miR-9-3 expression that targets E-cadherin (CDH1), a cellular adhesion protein essential for the cell-cell contact of the gastric epithelium, and promoting tumor cell migration and invasion, leading to EMT in GC." (PMID 32150871, 2020). "In the primary tumor, most CNV were found in MYC, CCND1, ERBB2 and CCNE1." (PMID 33298978, 2020). "The last observation is consistent with a difference in the mechanisms underlying the anti-tumor action of ATRA in MB-157 and HCC-1599 cells, indicating that MYC-targeting is not a major determinant of the MB-157 growth-inhibitory response to the retinoid." (PMID 33081033, 2020). "The mean MYC copy number in tumor samples was 2.25 with an SD of 0.53 and in nontumor samples 2.00 with an SD of 0.09." (PMID 33014186, 2020). "Finally, we focused on patient 21, with a pT3N0 intestinal histologic subtype tumor arising from the gastric antrum characterized by gains of EGFR, MYC (OMIM 190080) KRAS, MET, and PIK3CA by OncoScan (eFigure 4C in the Supplement)." (PMID 32338752, 2020). "It is noteworthy that the USP28 targets c‐JUN and c‐MYC were not downregulated in established tumours in KPLU mice, when compared to KPL." (PMID 32128997, 2020). "Molecularly, MYC and TBX3 could be partially responsible for ZFHX3′s promoting cell proliferation and tumor growth effects." (PMID 33217982, 2020).
tumor (continued). "The addition of 0.4 μM dox decreased expression of androgen targets and induced genes involved in DDR, lipoprotein signaling, and cholesterol metabolism, with MYC targets downregulated and cell cycle genes dysregulated, thus confirming the LAPC-4 xenograft tumor results." (PMID 32198885, 2020). "We summarize below the direct and indirect connections found between MYC and UPR activation in different cancers and propose that MYC and UPR activation may work together to foster tumor progression." (PMID 32310340, 2020). "RNA-seq data also showed that THZ1 could diminish transcripts of MYC-targeted genes, such as HK2, CDC25A, GLUT1 (SLC2A1), PD-L1 (CD274), BRCA1, and BRCA2, which are important mediators of MYC’s function in tumor metabolism, immune evasion, and DNA repair." (PMID 32690037, 2020). "Methylated H19 RNA may compete with MYC mRNA for binding to G3BP1, promoting tumor cell progression." (PMID 32978516, 2020). "Furthermore, using ChIP-qPCR on PDX tumor tissue, we detected AR, DOT1L and H3K79me2 at this MYC enhancer in addition to the active enhancer marks H3K27ac and H3K4me2 and RNA polymerase II (Pol II)." (PMID 32814769, 2020). "In addition to offering insight into the function of PRC2 in tumour initiation, our data suggest that H3.3K27M drives cancer by extensive transcriptome remodelling, centred on epigenetic activation of a RAS/MYC axis." (PMID 33277484, 2020). "Tunicamycin can induce the ER stress, we also treated the MYC-ON mice with Tunicamycin plus BFA and found that co-treatment with the two inhibitors can further reduce the tumor number (MYC-ON/DMSO: 63.0 ± 18.0; MYC-ON/BFA: 16.8 ± 7.5; MYC-ON/Tuni: 47.3 ± 19.8; MYC-ON/BFA+Tuni: 5.8 ± 5.0)." (PMID 31924786, 2020). "Since MYC-activated cells secrete factors, which can induce an MYC-dependent metabolic program in CAFs, JQ1 might be able to interfere with the tumour cell-CAF crosstalk." (PMID 32481570, 2020). "The B2 sample was randomly chosen out of a pool of six tumor samples (four ALL, one BL, one Burkitt’s-ALL) which could potentially harbor a BCR-ABL1, IGH/MYC, or CRLF2-P2RY8 rearrangement." (PMID 32504042, 2020). "We concluded that downregulation of the BASP1 gene is a necessary event in MYC‐induced oncogenesis and that the BASP1 protein may act as a potential tumor suppressor." (PMID 31944520, 2020). "The CCK-8 assay results showed that IC50 of anti-tumor drug doxorubicin on KG-1 cells was decreased, and drug-resistant proteins MRP1 and P-GP showed down-regulated expression after silencing XIST, which was rescued by overexpression of MYC (all p < 0.05)." (PMID 33228517, 2020). "Interestingly, instead of MYC, calcium-dependent phospholipid-binding protein ANXA2 was downregulated in PD tumor of old men forming a key central node." (PMID 33575208, 2020). "Moreover, we detected 15 gene amplifications in six different tumor specimens, including AR, CCND1 (n = 2), FGF19 (n = 2), FGF3 (n =2), KRAS (n = 2), MYC (n = 2), CCND3, CCNE1, CDK6, and RICTOR." (PMID 33203166, 2020). "In line with a recent study, we showed that THZ1 could suppress tumor glucose metabolism in NSCLC cells, which may depend on downregulating MYC-targeted genes including HK2, GLUT, and CDC25A." (PMID 32690037, 2020). "In addition, tumor signaling pathways that are regulated by BRAF, HIF-1α, c-MYC, and mTOR are accelerated to activate glycolysis in the cancer cells and accumulation of lactate in the microenvironment of the tumor." (PMID 32213878, 2020). "Interestingly, when comparing these three MYC proxisome studies done in HeLa cells and HEK293 cells/tumor xenografts, a large overlap of 62 candidates can be observed despite the disparity of cellular systems." (PMID 32477404, 2020). "In order to investigate the status of tumor-infiltrating lymphocytes, TIMER database was employed to explore whether the MYC expression was correlated with immune infiltration levels in CRC." (PMID 33193630, 2020).
tumor (continued). "We further checked the protein expression of TRIB3, ALDH1A1, and c-MYC in lysates of xenografted tumors and results showed that TRIB3 was slightly decreased in the only one small engrafted tumor of TRIB3-knockdown AN3CA cells, while the expression levels of ALDH1A1 and c-MYC were greatly reduced." (PMID 33334065, 2020). "In vivo, we could show that in MYC-induced liver tumors, HES5 repressed tumor growth, whereas in AKT-induced liver tumors, HES5 promoted tumor formation." (PMID 32055024, 2020). "Molecularly, ZFHX3 could bind to the promoters of MYC and TBX3 to activate their transcription, which could then partially mediate ZFHX3′s effects on cell proliferation and tumor growth." (PMID 33217982, 2020). "Amplification of MYC gene can lead to tumor progression, chemotherapy tolerance, and poor clinical outcome, but the understanding of how these three MYC oncogenes affect the processes has not yet been determined." (PMID 32281704, 2020). "Based on these encouraging data and in the light of the problems in directly targeting the c-MYC protooncogene, the use of FASN inhibitors might represent a valid therapeutic approach for HCC, at least in the tumor subset showing activation of c-MYC." (PMID 33187130, 2020). "In addition, AKT2 (p = 0.002) and KAT6A (p = 0.015) amplifications were more frequent in tumor samples from younger patients (<60), and CEBPA (p = 0.028) and MYC (p = 0.023) amplifications were more common with advanced (stage III and IV) disease stage." (PMID 32877461, 2020). "Against this possibility, the tumor burden in the liver was not statistically different between MYC and MYC/Twist1 mice." (PMID 31933479, 2020). "The lack of c‐MYC/8q24 rearrangements, as well as cyclin D1 and MYC expression in the tumor cells allowed for a diagnosis of DLBCL." (PMID 32100426, 2020). "On the other hand, iPSCs generated without c-MYC virus show decreased tumor frequency but also a reduced efficiency of iPSC generation." (PMID 33198288, 2020). "As cancer cells acquire metabolic adaptations in response to a variety of cell-extrinsic and cell-intrinsic cues, a single model of MYC-driven tumor metabolism does not describe the sum of metabolic changes that support cell growth." (PMID 32651356, 2020). "A tumor suppressor role was confirmed for miR-26b-5p, and this effect could at least in part be attributed to KPNA2, a known regulator of OCT4, c-jun, and MYC." (PMID 32512858, 2020). "Unlike MKK3 and MYC, p38 upregulation does not correlate with either the overall tumor-to-stroma ratio (Spearman R = −0.22, p-value = 0.13, q-value = 0.47) or the number of discrete tumor nests (Spearman R = 0.24, p-value = 0.10, q-value = 0.47)." (PMID 32873298, 2020). "Tumor cell proliferation is also supported by PKM2-dependent phosphorylation the Thr11 of histone H3, favoring its acetylation, and the removal of HDAC3 (histone deacetylase 3) from CYCLIN D1 and MYC promoters." (PMID 33008042, 2020). "Tumor cell proliferative index (phospho histone three expression) and apoptosis (cleaved caspase three) between MYC- and MYC/Twist1-HCC were not different." (PMID 31933479, 2020). "For example in tumor P22 (basal), three focal amplicons encompassing the VEGFA, MYC and CCNE1 loci were found in varying proportions and in certain instances (VEGFA and CCNE1) in a mutually exclusive manner in sequenced single-nuclei (p-value=0.003 – Fisher’s Exact Test)." (PMID 32401198, 2020).